SPARC (secreted protein acidic and cysteine rich)
Diseases named in the same sentence as SPARC in open-access papers (continued):
Sharing a sentence is not in itself a finding about the gene and the disease.
brain tumor (12 papers, 2012 to 2025). "In particular, as SPARC overexpression is associated with malignancy in brain tumor cells, the use of albumin could be expected to take advantage of the presence of SPARC to increase ICG accumulation in tumors." (PMID 36614294, 2023). "In the case of brain tumors, it has been reported that the expression of the SPARC protein is involved in the progression of malignant tumors." (PMID 36614294, 2023). "As a potential candidate for invasion-boosting, and enriched in its initial stage of developing a brain tumor, SPARC has been found and described." (PMID 36015199, 2022). "In the human brain, SPARC is expressed in reactive human astrocytes proximal to brain tumours and was shown to be increased in cases of human epilepsy." (PMID 24551460, 2014). "Within primary brain tumors, components such as vitronectin, osteopontin, tenascin-C, SPARC and BEHAB can be found, and some of them are upregulated and modulate brain tumor growth, proliferation and invasion." (PMID 22973309, 2012). "Therefore, when performing fluorescence-guided surgery based on the SPARC target ICG-HSA complex in malignant brain tumors, it is expected to be a promising solution for surgeons by making it possible to identify the SPARC-positive region of cancer." (PMID 36614294, 2023). "The two activated UPRs specific to GL261(scid) tumor responses have glial cell-related functions: DMD may relate to glial cell differentiation; and SPARC can inhibit brain tumor cell growth but also promotes invasion by increasing binding of extracellular matrix proteins." (PMID 27515027, 2016). "we have reported five co-regulated clusters via seven important co-expression genes (COL1A2, LUM, SPARC, THBS2, IL1B, CXCL8, THY1) interacting between five clusters of the brain tumours." (PMID 35045088, 2022).
medulloblastoma (12 papers, 2010 to 2024). A malignant, invasive embryonal neoplasm arising from the cerebellum. "A total of 6 biological signaling pathways were significantly associated with SPARC mediated expression in medulloblastoma cells (p < 0.05)." (PMID 28435518, 2017). "In this study, we examined the effects of SPARC on medulloblastoma tumours in vitro and in vivo and whether inhibition of angiogenesis is implicated in the anti-tumour effect of SPARC." (PMID 20087345, 2010). "Overexpression of SPARC induces apoptosis in medulloblastoma by triggering ER stress and UPR; and in neuroprimitive neuroectodermal tumors (PNET) through different pathways." (PMID 38254665, 2024). "In medulloblastoma, SPARC overexpression decreased STAT3 phosphorylation, leading to cell cycle arrest and neuronal differentiation." (PMID 33932101, 2021). "Our previous studies have shown that SPARC expression was very low in human medulloblastoma tissue samples when compared with normal cerebellum tissue samples." (PMID 28435518, 2017). "We performed pathway analysis using PANTHER database in order to understand which signaling pathways are altered with SPARC expression in medulloblastoma cells." (PMID 28435518, 2017). "Our studies also showed that SPARC enhances radiotherapy response in medulloblastoma in vitro and in vivo." (PMID 28435518, 2017). "A very remarkably different clustering pattern was observed in SPARC overexpressed versus SPARC under expressed medulloblastoma samples compared to parental/control medulloblastoma samples." (PMID 28435518, 2017). "We therefore performed global expression analysis for microRNAs using miRNA microarray to explore the miRNAome in SPARC expressed medulloblastoma and control cells." (PMID 28435518, 2017). "In conclusion, we established that SPARC expression modulated microRNA profile in medulloblastoma cells." (PMID 28435518, 2017). "Fluorescence activated cell sorting (FACS) analysis indicated that SPARC expressed cells were arrested in G2/M phase compared to mock or empty vector treated controls in medulloblastoma cells." (PMID 28435518, 2017). "Total protein and total RNA was isolated from the cells at 36 h after post-transfection, and immune blot analysis and qRT-PCR was performed to detect SPARC expression levels in medulloblastoma cells." (PMID 28435518, 2017). "In this study, we identified the miRNA expression profile in SPARC overexpressed human medulloblastoma cells using microarray technology." (PMID 28435518, 2017). "We constructed molecular networks with the 81 unique mRNAs predicted to be regulated by 6 differentially expressed miRNAs in SPARC expressed medulloblastoma cells using the IPA." (PMID 28435518, 2017). "We also showed that SPARC expression inhibits medulloblastoma tumor growth in an intracranial mouse model." (PMID 28435518, 2017). "addition, SPARC significantly increased TUNEL-positive apoptotic cells in D283 medulloblastoma cells in a concentration dependent manner." (PMID 28435518, 2017). "We found more than 3-fold increase in relative SPARC protein and mRNA transcript expression in D283 medulloblastoma cells as compared to parental (mock) and empty vector (pEV) controls (p < 0.01)." (PMID 28435518, 2017). "We previously demonstrated that human medulloblastoma tissue samples expressed very low or minimal levels of SPARC when compared with normal cerebellum." (PMID 28435518, 2017). "Previously, we reported that SPARC expression significantly impairs medulloblastoma tumor growth in vitro and in vivo and also alters chemo sensitivity." (PMID 28435518, 2017). "Further, we also showed that SPARC altered cisplatin sensitivity by modulating the Let-7f-1 miRNA/ HMGB1 axis in medulloblastoma cells." (PMID 28435518, 2017). "We used custom multi-species microarrays containing 1209 probes covering 1220 human mature miRNAs, to detect differentially expressed miRNAs in SPARC overexpressed D283 medulloblastoma cells." (PMID 28435518, 2017).
medulloblastoma (continued). "We have previously demonstrated that SPARC stimulates neuronal differentiation of medulloblastoma cells by suppressing Notch signaling." (PMID 28435518, 2017). "Herein, we assessed microRNA (miRNA) profiling to identify the functional network and biological pathways altered in SPARC-overexpressed medulloblastoma cells." (PMID 28435518, 2017). "It has been previously demonstrated by the authors that SPARC overexpression leads to autophagy-mediated apoptosis in medulloblastoma." (PMID 23123816, 2013). "In medulloblastoma cells, SPARC overexpression inhibited angiogenesis leading to the decrease of tumour growth." (PMID 22957090, 2012). "In medulloblastoma, the overexpression of SPARC can inhibit the angiogenesis in tumour by lowering the expression and secretion of VEGF and MMP-9." (PMID 22957090, 2012). "To elucidate the role of SPARC, we enhanced SPARC expression in medulloblastoma cells using stable transfection and expression constructs with SPARC full-length cDNA driven by a CMV promoter." (PMID 20087345, 2010). "This study reports that SPARC expression results in a significant decrease in angiogenic capacities in vitro and in vivo and remarkably reduces in vivo tumourigenicity of medulloblastoma cells." (PMID 20087345, 2010). "We therefore examined the possible role of MMP-9 in the anti-angiogenic effect of SPARC-overexpressed Daoy medulloblastoma cells." (PMID 20087345, 2010). "We therefore sought to determine the effect of SPARC expression on medulloblastoma tumour growth and angiogenesis." (PMID 20087345, 2010). "The SPARC expression reduced xenograft growth with reduced vascularity in an orthotopic medulloblastoma model." (PMID 20087345, 2010). "Using the Daoy cell line stably transfected with SPARC cDNA, we determined the contribution of SPARC in medulloblastoma tumour growth." (PMID 20087345, 2010). "We also analysed the effect of MMP-9 on the in vivo consequences of SPARC expression on medulloblastoma tumour formation in nude mice." (PMID 20087345, 2010). "This study provides an insight into the possible functional roles of SPARC in medulloblastoma tumour angiogenesis, and the data demonstrate that SPARC expression is inversely correlated with medulloblastoma tumour growth in vivo." (PMID 20087345, 2010). "Also, SPARC activates autophagy-mediated apoptosis in medulloblastoma and neuroblastoma primitive neuroectodermal tumor (PNET) cells via different pathways." (PMID 33584170, 2020). "miR-181 expression was also enhanced in SPARC expressed medulloblastoma cells compared to controls." (PMID 28435518, 2017). "We have previously shown that SPARC enhances radio response in medulloblastoma." (PMID 28435518, 2017). "We also demonstrate increased expression of miR-204 in SPARC overexpressed medulloblastoma cells." (PMID 28435518, 2017). "qRT-PCR was performed on miR-125b-1* (FC = 1.57), miR-181a-5p (FC = 2.21), miR-146a-5p (FC = 1.68), miR-204-5p (FC = 1.57), miR-509-3p (FC = 1.73) and miR-219-5p (FC = 1.57) in SPARC overexpressed medulloblastoma cells (pSPARC) compared to empty vehicle (pEV) treated control samples." (PMID 28435518, 2017). "Therefore, the focus of this investigation was to determine the role of SPARC in medulloblastoma (i.e., the possibility of its use as a therapeutic target or agent)." (PMID 20087345, 2010). "To experiment with a genetic approach to induce SPARC expression and observe its effects on medulloblastoma tumour growth in vitro and in vivo, we cloned a human SPARC cDNA in a pcDNA3.1 mammalian expression vector and transfected it into Daoy parental (Daoy-P) cells." (PMID 20087345, 2010). "However, it remains to be determined whether mir-204 induces autophagy in SPARC mediated autophagy in medulloblastoma cells." (PMID 28435518, 2017).
medulloblastoma (continued). "This is consistent with our previous studies demonstrating that SPARC expression suppressed proliferation and induced neuronal differentiation in medulloblastoma cells suggesting that mir-125b could be a key player in SPARC mediated tumor suppressive effects in medulloblastoma cells." (PMID 28435518, 2017). "Therefore, in medulloblastoma, SPARC expression is inversely correlated with malignant phenotype." (PMID 20087345, 2010). "In the literature, SPARC overexpression has been correlated with six miRNAs involved in medulloblastoma progression, whereas the reciprocal modulation between VEGFA and SPARC proteins has been related to tumor growth." (PMID 39000404, 2024). "Further, we also demonstrated that SPARC overexpression increased caspase-3 and caspase-8 activities and enhanced PARP cleavage when compared to mock or an empty vector controls in D283 medulloblastoma cells." (PMID 28435518, 2017). "We developed three human medulloblastoma cell lines designated as Daoy-SP1/2/3, which stably express human SPARC cDNA." (PMID 20087345, 2010). "Furthermore, we also showed that SPARC protein and mRNA levels were increased up to 3–4-folds in D425 and UW228 medulloblastoma cell lines transfected at a 2 μg/ml of pSPARC compared to controls." (PMID 28435518, 2017). "Furthermore, SPARC overexpression induced a decreased expression of MMP9 and an increase of TIMP3 in medulloblastoma tumor." (PMID 23935929, 2013).
breast tumors (11 papers, 2006 to 2023). "Statistical analysis of tissue microarray data showed that upregulation of SPARC occurs in basal-like breast tumors." (PMID 28425924, 2017). "In this work, it was found that SPARC gene is little or not expressed in the normal breast tissue resistant to breast carcinogenesis, from mice treated with Maitake Pro4X, whereas SPARC was highly expressed in breast tumor tissues." (PMID 27401257, 2016). "SPARC gene expression was up‐modulated in the breast tumor tissues treated or untreated (control, 33.5 ± 0.70) with Maitake Standard (43.0 ± 0.90) or Pro4X (37.25 ± 0.70)." (PMID 27401257, 2016). "Consistent with our previous study, SPARC was a prominent gene in ECM3 gene classification of breast tumors." (PMID 23441215, 2013). "SPARC expression was detected in 17/17 human breast tumour biopsies and to a lesser extent in some established cell lines." (PMID 16626496, 2006). "Moreover, studies on mouse models have shown that the expression of stabilin-1 induced tumor growth and helped tumor cells acquire invasive capability by endocytosis of antitumoral matricellular glycoprotein SPARC in breast tumors." (PMID 31302753, 2020). "Moreover, SPARC expression was previously shown to be elevated in approximately 5% of malignant epithelial cells within breast tumors and a prognostic indicator of poor outcome." (PMID 27622658, 2016).
glaucoma (11 papers, 2008 to 2024). Increased pressure in the eyeball due to obstruction of the outflow of aqueous humor. "The matricellular protein SPARC is associated with excessive wound healing, increased fibrosis, and scar formation in glaucoma pathogenesis." (PMID 30534608, 2018). "SPARC (secreted protein, acidic and rich in cysteine) is a matricellular protein associated with increased fibrosis and glaucoma pathogenesis." (PMID 25216052, 2014). "We further demonstrate in vivo, by the use of a murine model of glaucoma filtration surgery, that SPARC deficiency can maintain the surgically-induced wound for a longer period of time compared to WT." (PMID 20195533, 2010). "Recently, it has been found that SPARC deficiency in mice resulted in improved surgical survival in a mouse model of glaucoma filtration surgery." (PMID 21042566, 2010). "Further investigations are warranted to unravel the involvement of SPARC in the pathogenesis of glaucoma, and also to identify the causal gene at GLC1M for JPOAG." (PMID 21042566, 2010). "Network pharmacology identified SPARC as a gene associated with glaucoma pathogenesis." (PMID 37577749, 2023). "The influence of SPARC on TGF-β2-mediated ocular hypertension offers a violent disease connection to primary open-angle glaucoma (POAG) pathogenesis." (PMID 37577749, 2023). "SPARC has become a good target for the treatment of a series of ophthalmic diseases, such as glaucoma, and will bring good news to patients in the future." (PMID 37577749, 2023). "As in vivo data showed a reduced IOP (up to 15–20%) in SPARC-null mice, SPARC is assumed to be involved in glaucoma pathogenesis." (PMID 34208432, 2021). "In the eye, an increased SPARC level has been correlated with cataract, corneal wound repair, proliferative diabetic retinopathy, and glaucoma." (PMID 21976959, 2011). "We have therefore provided evidence for the first time of a novel role for SPARC depletion as a promising effective therapeutic method for preservation of wound filtering function in glaucoma filtration surgery." (PMID 20195533, 2010). "In the trabecular meshwork of postmortem human eyes, SPARC and another glaucoma gene MYOC responded significantly to elevated-IOP." (PMID 21042566, 2010). "Inhibition of SPARC expression should be considered as a therapeutic tool to improve glaucoma filtration surgical outcome." (PMID 20195533, 2010). "Further investigations are warranted to unravel the involvement of SPARC in the pathogenesis of other forms of glaucoma." (PMID 21042566, 2010). "The evidence presented in this report is strongly supportive for the targeting of SPARC to increase the success of glaucoma filtration surgery." (PMID 20195533, 2010). "In this study, we investigated post-operative surgical wound survival in an experimental glaucoma filtration model in SPARC-null mice." (PMID 20195533, 2010). "The purpose of this study was to evaluate the expression of SPARC in iris tissue from primary angle closure glaucoma (PACG) eyes." (PMID 18949063, 2008). "The PACG iris expressed SPARC 13.6-fold more and collagen I 5.2 fold more compared to non-glaucoma control iris." (PMID 18949063, 2008). "SPARC remains a prospective index for the treatment of glaucoma." (PMID 37577749, 2023). "For the treatment of glaucoma, SPARC knockout has emerged as an attractive option." (PMID 37577749, 2023). "CTGF and SPARC have also been documented as culprits in ocular hypertension and glaucoma." (PMID 32973273, 2020). "Our results provide evidence that SPARC may be involved in excessive wound healing of human Tenon’s capsule after glaucoma surgery." (PMID 21264231, 2011). "Whether the SPARC levels in glaucoma patients is correlated with the success rate of filtration surgery is unknown." (PMID 21042566, 2010). "SPARC may be considered a potential target for treating glaucoma." (PMID 37577749, 2023).
glaucoma (continued). "Together with observations in SPARC−/− mice after filtration surgery it is tempting to speculate that a modulation of SPARC expression could be a feasible therapeutic approach to reduce excessive scarring and subsequently to prevent failure of glaucoma filtration surgery." (PMID 21264231, 2011). "No study has yet evaluated the involvement of SPARC mutations in human glaucoma." (PMID 21042566, 2010). "So far, the involvement of the SPARC protein level in the pathogenesis of glaucoma is unknown." (PMID 21042566, 2010). "In glaucoma, elevated SPARC expression has been detected in the iris of POAG and primary angle closure glaucoma patients." (PMID 21042566, 2010). "Furthermore, elevated expression of SPARC has been detected in the iris of POAG patients, although whether such change was a cause or consequence of glaucoma, or just a phenomenon secondary to the use of topical medications for glaucoma remained unverified." (PMID 21042566, 2010). "The expression of SPARC was significantly higher in PACG iris specimens with a 3.3 fold and 13.6 fold higher expression than in POAG and non-glaucoma iris specimens, respectively." (PMID 18949063, 2008). "The expression levels of SPARC and collagen I in PACG, POAG, and non-glaucoma iris specimens were analyzed by real-time RT–PCR." (PMID 18949063, 2008). "In this study, we found a significant increase in the expression of SPARC in the iris tissue of PACG eyes compared to POAG and non-glaucoma eyes." (PMID 18949063, 2008). "A higher level of SPARC expression in individual iris specimens from PACG eyes compared to both POAG iris specimens and non-glaucoma controls was observed as represented by Ct values normalized against the respective β-actin Ct values (∆Ct)." (PMID 18949063, 2008). "The lack of SPARC reduces intraocular pressure in a glaucoma mouse model." (PMID 37577749, 2023). "Since basal and TGF-β-mediated expression of extracellular matrix components is increased in HTF cells of patients having PEX glaucoma or POAG, it is of particular interested if this is also true for SPARC expression and hereby a TGF-β independent scarring response could be mediated." (PMID 21264231, 2011). "Although some members, e.g., the 3-year-old unaffected subject, may develop glaucoma later in life, it is likely to be independent of SPARC." (PMID 21042566, 2010). "Therefore, although SPARC by itself is a good candidate gene for glaucoma, it may not be responsible for JPOAG in the pedigree." (PMID 21042566, 2010). "Hence, future work involves the development of effective SPARC siRNA(s) as well as efficient delivery systems for it so as to improve the survival of the filtering bleb without the need for anti-proliferatives in glaucoma filtration surgery." (PMID 20195533, 2010).